SCN1A (sodium voltage-gated channel alpha subunit 1)
Diseases named in the same sentence as SCN1A in open-access papers (continued):
Sharing a sentence is not in itself a finding about the gene and the disease.
Dravet syndrome (continued). "A gene-based collapsing analysis highlighted an increased variant burden in CHD2, FLNA and TSC1 (P < 0.05) in Dravet syndrome compared with GEL SCN1A controls that was not significant after correction for multiple comparisons." (PMID 37006128, 2023). "Using transcranial magnetic stimulation Stern and colleagues showed a significant lack of GABAa-mediated inhibition in patients with Dravet syndrome (SCN1A mutation carriers)." (PMID 36639812, 2023). "Collectively, for differentiation from SCN1A‐positive Dravet syndrome at onset, it is noteworthy that there are fewer hemiclonic seizures, and they occur as clustered patterns based on our findings, in addition to the well‐known afebrile and short‐duration seizures." (PMID 36775847, 2023). "Mutations in SCN1A are associated with different neurological diseases, from the relatively mild genetic epilepsy with febrile seizures plus (GEFS+) to the severe myoclonic epilepsy in infancy (SMEI), also known as Dravet syndrome (DS), OMIM 607208." (PMID 37819378, 2023). "In order to assess whether the increased Gpr55 expression of F1.Scn1a+/- mice contributes to the Dravet syndrome phenotype, we generated F1.Scn1a+/- mice with heterozygous deletion of Gpr55 (F1.Scn1a+/;Gpr55+/-)." (PMID 36701411, 2023). "In the present study, we investigated whether the phenotype of the Scn1a+/− mouse model of Dravet syndrome includes ictal vocalizations." (PMID 36811143, 2023). "We then determined whether heterozygous deletion of Gpr55 is anticonvulsant in the F1.Scn1a+/- mouse model of Dravet syndrome." (PMID 36701411, 2023). "Here we sought to examine whether the orphan receptor Gpr55 could be a genetic modifier and potential novel drug target in the Scn1a+/- mouse model of Dravet syndrome." (PMID 36701411, 2023). "Quantitative audio analysis could be developed as a seizure detection tool for the Scn1a+/− mouse model of Dravet syndrome." (PMID 36811143, 2023). "However, the symptoms of Dravet syndrome can be worsened if treated with sodium-blocking drugs and should therefore be avoided in SCN1A-positive patients." (PMID 37834053, 2023). "Here we assessed whether Gpr55 contributes to the strain-dependent seizure phenotypes of the Scn1a+/- mouse model of Dravet syndrome." (PMID 36701411, 2023). "Since developmental problems might not be evident at onset, some clinical features at onset could overlap between PRRT2‐positive SeLIE and SCN1A‐positive Dravet syndrome." (PMID 36775847, 2023). "However, in Zebrafish, the scn1a mutant model of Dravet syndrome antagonistic ligand regulation of Sigma1R attenuates epileptiform behavior." (PMID 37298532, 2023). "Eight individuals with Dravet syndrome and SCN1A variants with FCD, six with histopathological confirmation, have been described.51–55 To our knowledge, in these reports, only SCN1A sequencing was undertaken." (PMID 37006128, 2023). "We also tested the effect of the Kcnt1 ASO in Scn1a+/− mice, a model of Dravet Syndrome." (PMID 37901435, 2023). "Since Dravet syndrome patients typically present with febrile seizures that then progress to spontaneous afebrile seizures, we model this progression by priming F1.Scn1a+/- mice with a hyperthermia-induced seizure at P18 and then measuring subsequent spontaneous seizure frequency." (PMID 36701411, 2023). "Dravet syndrome patients and F1.Scn1a+/- mice have a significantly reduced lifespan." (PMID 36701411, 2023). "Interestingly, a similar approach using defective Zinc Finger Nucleases fused to a transcriptional activator targeted to the Scn1a promoter has also been shown to be effective in a mouse model of Dravet syndrome." (PMID 37662470, 2023). "None of the variants identified in Dravet syndrome overlapped with variants in the GEL SCN1A controls." (PMID 37006128, 2023). "One study evaluated the effect of PER on a mouse model of Dravet syndrome (SCN1A E1099X/+)." (PMID 37483446, 2023).
Dravet syndrome (continued). "Our study does have limitations, including that we could not ascertain the effects of homozygous deletion of Gpr55 on seizure phenotypes of the Scn1a+/- mouse model of Dravet syndrome." (PMID 36701411, 2023). "We explored whether particular differences between ultra-rare SCN1A missense variants identified in the Dravet syndrome and GEL SCN1A control cohorts might explain differences in phenotype between these groups." (PMID 37006128, 2023). "Thirty-four adults with SCN1A-related Dravet syndrome were included; 28 were of European ancestry." (PMID 37006128, 2023). "Similarly, increased anxiogenic-like behaviors and cognitive impairments were detected in the Scn1a +/− mouse model of Dravet syndrome, as well as in chemical models of limbic seizures induced by chronic and sub-chronic pentylenetetrazole (PTZ) administration." (PMID 35203625, 2022). "Thus, we confirmed that Scn1a ± mice recapitulated the majority of comorbidity found in Dravet syndrome patients." (PMID 34980259, 2022). "Thus, we investigated the effect of inhibition of eEF2K on the epileptic and behavioral phenotype of Scn1a ± mice, a murine model of Dravet Syndrome." (PMID 34980259, 2022). "Dravet syndrome (DS) is a catastrophic form of pediatric epilepsy mainly caused by noninherited mutations in the SCN1A gene." (PMID 36240080, 2022). "Reduced dopamine transporter (DAT)‐binding was seen in the majority of the 39 GNDs with available dopaminergic imaging results, but not in Rett syndrome, Dravet syndrome (SCN1A), dihydropteridine reductase deficiency, and CLTC." (PMID 36699000, 2022). "Although a large majority of patients with Dravet syndrome have an SCN1A gene mutation, approximately 20% of the patients do not have an identified pathogenic variant in SCN1A." (PMID 36291443, 2022). "STK-001 is designed to upregulate the expression of the Nav1.1 protein that is encoded by the sodium channel, voltage-gated, type I, alpha subunit (SCN1A) gene, the mutations of which are responsible for a reduction in the expression of Dravet syndrome." (PMID 35213992, 2022). "The studies identified several genetic modifiers such as Hlf, the gene encoding hepatic leukemia factor, Cacna1g, the gene encoding Cav3.1 and Gabra2, the gene encoding the GABAA receptor α2 subunit that influence the phenotypes and severity of Scn1a+/− mouse model of Dravet syndrome." (PMID 35571373, 2022). "The objective of this study was to interrogate the anticonvulsant potential of Δ9-THCA in various seizure models—the Scn1a+/− mouse model of Dravet syndrome, the 6-Hz model of psychomotor seizures and the maximal electroshock (MES) model of generalized tonic-clonic seizures." (PMID 33998858, 2022). "SCN1A mutation‐induced genome‐wide transcriptomic dysregulation was assayed in tissue from an animal model rather than from people with Dravet syndrome." (PMID 36196775, 2022). "An ATP6V0C de novo variant had been reported in a SCN1A-negative patient with Dravet syndrome while the patient simultaneously harbored de novo missense variants in the genes of NKAIN3 and SLC8A1." (PMID 35600075, 2022). "The differences in the MRI scans of SCN1A and PCDH19 mutations have been documented in Dravet syndrome with initial normal brain MRI scans that eventually progressed to cortical or cerebellar atrophy, cortical dysplasia, and temporal lobe abnormalities at 2–3 years." (PMID 34833120, 2021). "We observed similar modifications in experimental traces, comparing cortical layer 2-3 fast spiking GABAergic neurons recorded in heterozygous Scn1a knock-out mice (Scn1a+/-), model of the developmental and epileptic encephalopathy Dravet syndrome, and wild type littermates as control." (PMID 34314446, 2021). "Furthermore, it was recently shown that antisense oligonucleotide treatment to decrease Scn8a (Nav1.6) expression was sufficient to rescue disease phenotypes in a Dravet Syndrome model of Scn1a haploinsufficiency." (PMID 34235638, 2021).
Dravet syndrome (continued). "We crossed VGAT-ChR2 mice with knock-out Scn1a+/– mice, which model the epileptic encephalopathy Dravet syndrome and in which one allele of the Scn1a gene is not functional, causing NaV1.1 haploinsufficiency and hypoexcitability of GABAergic neurons." (PMID 34491914, 2021). "A possibility for genetic epilepsy, and an as of yet untested strategy, could be to use CRISPR to destroy the splice-site of the recently discovered poison exon (20 N) in SCN1A, in order to permanently upregulate SCN1A expression in Dravet syndrome." (PMID 34235638, 2021). "However, the finding that four out of six (67%) Dravet syndrome/SCN1A cases display edema compare to 17% in the general epilepsy population is of interest and warrants further investigation." (PMID 32949224, 2020). "Epilepsy syndromes, such as generalized epilepsy with febrile seizures plus (GEFS+; Online Mendelian Inheritance in Man [OMIM] #604233), severe myoclonic epilepsy (SME) and SMEI, also known as Dravet syndrome (OMIM #607208), are associated with mutations in the SCN1A gene." (PMID 33013363, 2020). "We then examined the regulation of one‐carbon‐related amino acids in the brain of a mouse model of Dravet syndrome (Scn1A+/−), a CBD responsive condition in humans, and identified altered levels of glycine, methionine, and cysteine, implicating dysregulation of one‐carbon metabolism in this disease." (PMID 31693171, 2020). "Dravet syndrome is caused by dominant loss-of-function mutations in SCN1A which cause reduced activity of Nav1.1 leading to lack of neuronal inhibition." (PMID 32134913, 2020). "Zebrafish scn1a mutants exhibited spontaneous abnormal electrographic activity, hyperactivity and convulsive behaviors, so they can simulate the clinical phenotype of Dravet syndrome patients." (PMID 33198188, 2020). "Two pathogenic variants were observed in SCN1A but not in typical SCN1A-associated generalised epilepsy with febrile seizures or Dravet syndrome cases." (PMID 29760947, 2018). "In 2007, a 12-year-old girl who presented with PS, was reported to carry a sporadic missense mutation in sodium voltage-gated channel alpha subunit 1 (SCN1A), the gene encodes a voltage-gated sodium channel that was implicated in the pathology of Dravet Syndrome." (PMID 30319421, 2018). "In another study, 2 monozygotic twins presented with PS were found to have no mutations in the SCN1A gene or the GABRG2 gene (another gene associated with Dravet Syndrome)." (PMID 30319421, 2018). "Here we evaluated the effect of GS967 in the Scn1a+/− mouse model of Dravet syndrome." (PMID 28490751, 2017). "For example, a recent publication by Djemie and colleagues revisited patients who had presented with Dravet syndrome, typically associated with SCN1A variants, but had been SCN1A variant-negative after clinical sequencing." (PMID 28558813, 2017). "In addition to concern about the specificity of the effects seen to Scn1a in the zebrafish, I have concerns about the lengthy introduction and discussion of Dravet syndrome in humans." (PMID 27066534, 2016). "Altered metabolism is an important feature of many epileptic syndromes but has not been reported in Dravet syndrome (DS), a catastrophic childhood epilepsy associated with mutations in a voltage-activated sodium channel, Nav1.1 (SCN1A)." (PMID 27066534, 2016). "The SCN1A gene encodes the alpha subunit Nav1.1 of the voltage-gated Na+ channel and plays a crucial role in the pathogenesis of several monogenic epilepsy syndromes, including genetic epilepsy with febrile seizures plus (GEFS+) and Dravet syndrome." (PMID 26484865, 2015). "For example, in some mouse models such as the Dravet Syndrome SCN1a mutants, disrupting the gene in individual populations of neurons does not replicate the human phenotype, suggesting that an intact inhibitory/excitatory circuit is required for the full disorder." (PMID 26125563, 2015). "Of the children diagnosed with SCN1A-related Dravet syndrome, ten were males (66.7%; p = 0.31)." (PMID 23762420, 2013).
Dravet syndrome (continued). "Description of seizures following vaccinations in children with SCN1A-related Dravet syndrome." (PMID 23762420, 2013). "Furthermore, Dravet syndrome, one of the most severe forms of childhood epilepsy, is caused by mutations in SCN1A encoding Nav1.1 [reviewed in], or a mutation in SCN1B encoding Nav channel β1 subunit." (PMID 23834220, 2013). "A high percentage of SCN1A mutations was identified in our Chinese cohort of Dravet syndrome patients but none in the rest of patients." (PMID 22848613, 2012). "SCN1A-negative Dravet syndrome patients and patients with phenotypes resembling Dravet syndrome were checked for PCDH19 and TSPYL4 mutations." (PMID 22848613, 2012). "For example, Dravet syndrome, a severe early-onset disorder associated with poor cognitive outcome, and the milder generalized epilepsy with febrile seizures plus (GEFS+) syndrome are both caused by mutations in the SCN1A gene." (PMID 20502679, 2010). "Six of these Dravet syndrome patients with SCN9A missense variants also harbored either missense or splice site SCN1A mutations and three had no SCN1A mutations." (PMID 19763161, 2009). "In addition, we find supporting evidence for a multifactorial etiology of Dravet syndrome by uncovering concurrent variants in both SCN9A and SCN1A in a subset of our patients." (PMID 19763161, 2009). "The finding of variants in both SCN1A and SCN9A in a single patient led us to investigate whether additional disease-associated alleles in SCN9A contribute to Dravet syndrome." (PMID 19763161, 2009). "In this study, we used SNP microarrays to search for microrearrangements in patients with clinical features suggestive of Dravet syndrome but without mutations in SCN1A in order to identify new causative genes." (PMID 19214208, 2009). "An initial series of 41 probands (18 females and 23 males), referred for genetic analysis of Dravet syndrome but negative for point mutation and intragenic rearrangement of SCN1A, was screened for genomic rearrangement using Illumina 370CNV microarrays." (PMID 19214208, 2009). "However, unlike Dravet syndrome, now recognized as associated only with pathogenic variants in the SCN1A gene, EMAtS remains genetically heterogeneous." (PMID 41523187, 2026). "But variant identity, genic location, or variant class may not explain phenotypic diversity, with SCN1A variants in Dravet syndrome being an example." (PMID 40836506, 2026). "Importantly, sodium channel blockers (SCBs) are contraindicated in individuals carrying LOF variants but can be effective in those carrying GOF variants, and a specific treatment algorithm has been established for Dravet syndrome (DS), the most severe DEE linked to SCN1A mutations." (PMID 41515912, 2025). "In Dravet syndrome (DS; MIM607208), a severe form of DEE which is primarily caused by SCN1A haploinsufficiency, treatment in a DS mouse model with the antisense oligonucleotide STK-001 (also known as ASO-22) increases the production of functional Scn1a mRNA and Nav1.1 protein." (PMID 41244709, 2025). "Interestingly, the same treatment was effective also for Scn1a+/− mice, a Dravet syndrome model." (PMID 37654020, 2024). "No intronic variants in SCN1A were identified in two children with unsolved Dravet syndrome." (PMID 38129960, 2024). "Dravet syndrome (DS) is a developmental and epileptic encephalopathy (DEE), associated with variants in the voltage-gated sodium channel alpha 1 subunit (SCN1A) gene." (PMID 38737515, 2024). "To test the hypothesis that the background genetic architecture influences the phenotypic presentation of individuals with monogenic epilepsy, we used whole-genome sequencing (WGS) across a cohort of adults with clinically well-characterized SCN1A-related Dravet syndrome." (PMID 37006128, 2023).
Dravet syndrome (continued). "Nevertheless, we demonstrate that pathogenic variants in SCN1A do not necessarily act alone to produce the final phenotype: SCN1A may be the gene of major effect in Dravet syndrome, but it is not always the only gene, or only variant, of relevance." (PMID 37006128, 2023). "SCN1A-related Dravet syndrome (DS) is an early onset developmental and epileptic encephalopathy (DEE) characterized by multiple seizure types, cognitive decline, behavioral disturbances, and ataxia." (PMID 35414300, 2023). "Identification of pathogenic SCN1A variant is not mandatory for Dravet syndrome diagnosis." (PMID 36291443, 2022). "Furthermore, we propose that quantitative precision may be important when increasing SCN1A expression in current strategies aiming to treat seizures in conditions involving SCN1A haploinsufficiency, such as Dravet syndrome." (PMID 35551471, 2022). "As regards SCN1A, the splice-site c.695-1G>A variant was identified at the heterozygous state; it affects a splice acceptor site, is predicted as damaging by the in silico tools DANN and dbscSNV scores, and has already been reported as possibly associated with Dravet syndrome (MIM: #607208)." (PMID 36360260, 2022). "The pharmacological and potential therapeutic actions of CBGA are largely unknown, although a recent study from our laboratory demonstrated that CBGA has anticonvulsant properties in both the Scn1a+/- mouse model of Dravet syndrome and in the maximal electroshock (MES) seizure threshold test." (PMID 34980287, 2022). "Indeed, in a study of individuals with Dravet syndrome, one third of individuals who did not have a pathogenic mutation in SCN1A were found to harbor mutations in CHD2." (PMID 33435571, 2021). "The DEE Dravet syndrome (DS) is linked to de novo, monoallelic, loss‐of‐function (LOF) variants in SCN1A, encoding Nav1.1, although rare gain‐of‐function (GOF) variants have been reported." (PMID 32979291, 2020). "In a mouse model of Dravet syndrome with a hemizygous gene deletion (i.e., Scn1a +/-), it was observed that fast-spiking PV interneurons cells could no longer fire at their characteristically high frequencies, with a smaller but significant effect also observed in Sst-expressing Martinotti cells." (PMID 29069078, 2017). "Therefore, the total proportion of SCN1A-related Dravet syndrome among children with seizures following vaccination, might be slightly higher." (PMID 23762420, 2013). "In the three remaining Dravet syndrome patients without SCN1A mutations, additional proconvulsive genes that act in concert with SCN9A may yet be uncovered." (PMID 19763161, 2009). "Notably, acute encephalopathy may occur in patients with a SCN1A mutation but without Dravet syndrome, many of whom being apparently healthy prior to the onset of encephalopathy." (PMID 36761411, 2023). "Similarly, the frequent SD in Scn1a+/RX mice seems contradictory to the observation that migraine with aura, generally considered to be an SD-linked neurological symptom, is not common in Dravet syndrome patients." (PMID 37551713, 2023). "While the HPO includes ways to encode age-based features within broad categories such as “neonatal onset” or “childhood onset”, a more nuanced approach may be necessary to identify differences such as the later onset of Dravet syndrome when caused by variants in PCDH19 rather than SCN1A." (PMID 34031551, 2021). "AntagoNATs that upregulate SCN1A expression are currently in the IND-enabling stage at CuRNA/OPKO (Dravet Syndrome; CuRNA/OPKO, 2020)." (PMID 33996898, 2021). "Employing a mouse Scn1a+/− mutant to investigate a potential mechanism of CBD provided a logical approach, as this model reproduces seizure types found in patients with Dravet syndrome and Lennox–Gastaut syndrome." (PMID 31693171, 2020).